INS (insulin)
Diseases named in the same sentence as INS in open-access papers (continued):
Sharing a sentence is not in itself a finding about the gene and the disease.
steatosis (continued). "In ob/ob mice, adenoviral overexpression of BiP in the liver activates SREBP-1c, which reduces ER stress, increases insulin sensitivity, and decreases steatosis." (PMID 38137501, 2023). "Fasting serum triglycerides (TG) and insulin levels were significantly different across the three groups: normal liver, simple steatosis (SS), and non-alcoholic steatohepatitis (NASH) (p value < 0.05)." (PMID 36765383, 2023). "Skeletal muscle steatosis produces a much-reduced ability to consume glucose in response to insulin." (PMID 38260129, 2023). "Steatosis occurs as a consequence of increased lipogenesis, increased uptake of dietary fatty acids and carbohydrates, and adipose tissue insulin resistance and the flux of free fatty acids to the liver." (PMID 38060313, 2023). "Steatosis of these lean organs should translate into elevated liver gluconeogenesis, reduced muscle glucose uptake in response to insulin, and beta-cell apoptosis, leading to a declining pancreatic capacity to produce insulin." (PMID 38260129, 2023). "This review focuses on the mechanisms that contribute to the development of diet-induced steatosis in an insulin-resistant liver." (PMID 37242206, 2023). "Conversely, cytoplasmic lipolysis also decreases steatosis; however, in this case the ensuing production of cytoplasmic nonesterified fatty acids induces hepatic inflammation and systemic insulin resistance." (PMID 37443159, 2023). "In contrast, a diet rich in fat by itself induces resistance to insulin, obesity, and moderate steatosis with low inflammation and fibrosis." (PMID 38186528, 2023). "The leptin knockout mice, Lepob/Lepob (ob/ob), are obese, insulin resistant, and hyperglycemic, and show some degree of steatosis." (PMID 37377968, 2023). "Lipotoxicity impairs insulin signaling by promoting oxidative stress and reactive oxygen species (ROS) generation and by stimulating inflammatory pathways, leading to steatosis progression to NASH, fibrosis, and cirrhosis." (PMID 37998747, 2023). "Genetic and molecular studies, particularly in the context of non-alcoholic fatty liver disease (NAFLD), support a critical role for PTEN in hepatic insulin sensitivity and the development of steatosis, steatohepatitis, and fibrosis." (PMID 37511368, 2023). "We show that when steatosis is decoupled from impairments in insulin responsiveness, sex is a moderating factor that influences sucrose-driven lipid storage and the contribution of de novo fatty acid synthesis to the overall hepatic triglyceride pool." (PMID 36229459, 2022). "Mitochondrial malfunction, impaired fatty acid exportation, increased cytokine production and insulin resistance were suggested as possible mechanisms for the development of steatosis by chemical toxicants." (PMID 35622572, 2022). "This is in marked contrast to the insulin resistant Cc1−/− mouse that developed steatosis, inflammation, and fibrosis in aortic roots in the face of limited pro-atherogenic lipidemia when propagated on C57BL6/J background and fed a regular chow diet." (PMID 35457157, 2022). "Steatosis and insulin stimulus resulted in even higher P-ERK levels in HepG2 cells, proposing that steatosis primes cancer cells for proliferation and survival." (PMID 36009822, 2022). "Compared to AL mice, the AL-OLZ group exhibited gains in body mass and adiposity in peripheral insulin-sensitive organs, manifested as steatosis of the liver and skeletal muscle, and a deterioration in insulin sensitivity as detected by HOMA-IR." (PMID 35958660, 2022). "In fructose induced MAFLD, supplementation with amino such as citrulline or methionine positively modulate steatosis, fibrosis and inflammation likely by improving insulin sensitivity, lipid metabolism an oxidative stress." (PMID 36466421, 2022). "In our hypertensive patients, higher plasma insulin and HOMA-index were associated with greater LV mass and diastolic dysfunction, and their values increased with increasing number of steatosis scores." (PMID 36312275, 2022).
steatosis (continued). "The BMI value and serum levels of AST, ALT, UA, TC, insulin, and TB in severe steatosis group were higher than in healthy controls (all P < 0.05), and the serum HDL levels in patients with severe steatosis were lower than that in controls (P < 0.05)." (PMID 34986792, 2022). "In a study conducted on NAFLD patients, the effects of MD on steatosis and insulin sensitivity were examined; adherence to MD showed a significant reduction in steatosis." (PMID 35743545, 2022). "Several studies showed improvement in glycemic control by E4 in mice on HFD, along with reduction in endogenous insulin levels, hepatic lipid accumulation and protection from steatosis." (PMID 36012550, 2022). "The animals developed steatosis, lobular inflammation, and liver fibrosis while gaining significant weight and becoming insulin resistant." (PMID 35216100, 2022). "To corroborate these results, we verified the expression profiles of key genes involved in hepatic inflammation, insulin action, steatosis, and fibrosis in both up- and downregulated DEG lists, using a real-time qRT-PCR assay." (PMID 35700043, 2022). "Mice with whole-body deletion of the Gpx1 gene are protected from HFD-induced steatosis and liver damage attributed to improved hepatic insulin sensitivity." (PMID 35740032, 2022). "In this respect, metformin, despite raising hepatic sensitivity to insulin and reducing steatosis in a cohort of NAFLD individuals reached eventually insufficient results in a large meta-analysis." (PMID 35740032, 2022). "Rapamycin induces changes in circulating insulin and in hepatic gene expression that can contribute to the prevention of steatosis." (PMID 35986566, 2022). "We also noticed a trend to increase HDL, and to decrease LDL, ALT, fasting insulin, and degree of steatosis." (PMID 36296994, 2022). "Such DEG profiles are consistent with the improvement of insulin sensitivity and reduction in hepatic inflammation, steatosis, apoptosis, and fibrosis in NASH diet–fed MøFoxO1-KO mice." (PMID 35700043, 2022). "One study has shown that hepatitis C virus-infected cells have higher levels of CD2AP, which promotes hepatitis C virus transmission and steatosis by disrupting insulin signaling." (PMID 36359915, 2022). "vPrdx1 is the main PRDX family member in the pancreas, liver insulin resistance, inflammation and steatosis." (PMID 36619535, 2022). "The metabolic disturbance not only promoted steatosis and hepatocyte injury, but it also markedly suppressed insulin signaling and facilitated insulin resistance." (PMID 35217669, 2022). "The thiazolidinedione PPARγ agonist Pioglitazone (PIO) stimulates hepatic fatty acid oxidation and improves insulin sensitivity and reduces steatosis in NAFLD patients." (PMID 35203687, 2022). "A previous study reported that preoperative steatosis (p = 0.006) and insulin resistance index (p = 0.010) were independent predictors of postsurgical persistent severe steatosis one year after surgery via liver biopsy." (PMID 36619535, 2022). "Pioglitazone is an insulin sensitizer that acts on the peroxisome proliferator-activated receptor γ (PPARγ) to reduce steatosis by increasing lipid oxidation, thereby preventing NASH." (PMID 35958576, 2022). "PPARγ activation in diabetic patients improves whole-body insulin sensitivity at the same time increasing steatosis." (PMID 36520866, 2022). "Steatosis correlated with fasting insulin (p < 0.05), liver stiffness (p < 0.05), BMI (p < 0.001), and inversely with high-density lipoprotein cholesterol (p < 0.05)." (PMID 35892670, 2022). "SIRT2 has an overall positive effect in the liver, because it suppresses hepatic fibrosis and steatosis, and it counteracts ROS generation and mitochondrial dysfunction to restore insulin sensitivity." (PMID 33806509, 2021). "Concerning SGLT-2 inhibitors’ role on the glucagon-to-insulin ratio, they are able to improve it, therefore increasing ketogenesis in the liver and leading to protection against steatosis." (PMID 33921359, 2021).
steatosis (continued). "Components of the NAFLD-Liver Fat Score (fasting insulin, aspartate aminotransferase, and alanine aminotransferase) for suspected steatosis significantly improved at one and two years except for aspartate aminotransferase, which was statistically unchanged." (PMID 33652715, 2021). "A clinical trial showed that pioglitazone, apart from enhancing insulin sensitivity, also improved steatosis, inflammation, hepatocellular damage, and liver-enzyme levels of non-alcoholic steatohepatic patients." (PMID 33983968, 2021). "Preclinical studies have demonstrated that GLP-1 agonists are efficient in improving hepatic insulin sensitivity, steatosis and histology." (PMID 33921359, 2021). "Previous work indicated that increasing levels of SMs were observed in liver and serum in HFD-fed mice, because SM reduction ameliorates both insulin sensitivity and steatosis." (PMID 34200685, 2021). "Neuroligin family members have been found to stimulate insulin production, demonstrating the importance of neurohumoral regulation in steatosis." (PMID 34568346, 2021). "Inhibiting CYP4A can ameliorate steatosis through reduced endoplasmic reticulum stress and improved insulin signaling." (PMID 34768942, 2021). "Steatosis severity was associated with rising ALT and metabolic markers including triglycerides, insulin, fasting glucose and HbA1c." (PMID 34234198, 2021). "In this study, steatosis was induced by supplementation of 11 mM glucose, 1 mM fructose, 100 nM insulin and a mixture of 0.36 mM palmitate and oleate (GFIPO) and by the omission of fatty acids while increasing to 5 mM fructose (GFI)." (PMID 34959755, 2021). "Children with zone 1 steatosis had lower fasting triglyceride levels and lower fasting insulin according to the NASH report." (PMID 34479517, 2021). "In hepatocytes, hyperglycemic levels of glucose and insulin result in abnormal ectopic accumulation of lipids – a feature of steatosis." (PMID 34746700, 2021). "Previous studies in humans and animals demonstrated that LC administration improved insulin sensitivity related to reduction in steatosis." (PMID 34684533, 2021). "This inhibits glucose uptake by glucose transporter type 4 (GLUT-4), thereby increasing both blood glucose and insulin levels, leading to steatosis." (PMID 34680608, 2021). "Significant steatosis was associated with higher ALT (p < 0.05), triglycerides (p < 0.05), insulin level (p < 0.001), fasting glucose (p < 0.05) and HbA1c (p < 0.01)." (PMID 34234198, 2021). "Relationship between the degree of steatosis and the variables glycemia, insulin, HbA1c, and HOMA-IR pre- and post-treatment." (PMID 34136497, 2021). "Preclinical studies have demonstrated the efficacy of GLP‐1 agonists for the improvement in hepatic insulin sensitivity, steatosis and histology." (PMID 32704576, 2020). "Lean subjects in the Brazilian cohort were more insulin-resistant and had greater steatosis than subjects from other regions." (PMID 36419503, 2020). "Exercise not only improves cardiovascular health but also reduces steatosis, improves insulin sensitivity and modulates immune responses, promoting an anticancer immune microenvironment, and thus is an important component of lifestyle modification." (PMID 32443737, 2020). "Animal studies have shown that GLP-1 analogue therapy improves hepatic insulin sensitivity and decreases steatosis via direct binding to the hepatic GLP-1 receptor." (PMID 32566685, 2020). "Before and after the dietary intervention, all patients had the following measurements recorded: body mass, waist circumference, stage of steatosis, fatty liver index, liver enzymes, lipid parameters, insulin and glucose." (PMID 32028646, 2020). "Animal models of decreased hepatic MTTP activity have revealed an unexplained dissociation between hepatic steatosis and hepatic insulin resistance." (PMID 32907986, 2020). "Lipid levels, glucose, insulin, liver enzymes, steatosis, and fatty acid profiles of serum and erythrocytes phospholipids were assessed." (PMID 33374554, 2020).
steatosis (continued). "Proposed factors include diminished trophic effects of insulin, inflammation, fibrosis, and steatosis which are summarized in detail here." (PMID 32239341, 2020). "The Akt pathway has been shown to regulate reserve capacity, and it is likely that the liver is protected from steatosis and damage by increased use of the spare capacity in response to insulin-stimulated Akt upregulation." (PMID 33024056, 2020). "The disruption of hepatocyte-specific CD36 was shown to reduce liver lipid content and improve insulin sensitivity in high-fat diet-induced steatosis mice." (PMID 32443660, 2020). "Steatosis was associated with male sex, higher waist-to-hip ratio, lower high density lipoprotein (HDL) cholesterol and higher fasting insulin." (PMID 32720691, 2020). "In fact, mice that overexpress ChREBP exhibit improved insulin sensitivity and glucose tolerance despite having more pronounced hepatic steatosis." (PMID 32660130, 2020). "Steatosis, characterized by fat accumulation, represented the early stage of NAFLD and inflammation that interfered with the insulin signaling pathway is the key process that makes early steatosis develop into steatohepatitis." (PMID 32477116, 2020). "Normally, the amount of CB1R is low in liver tissue; however, under pathological conditions, the expression of CB1R in hepatic cells increases, thus contributing to hepatic insulin resistance, fibrosis, lipogenesis, and steatosis." (PMID 31035653, 2019). "Under pathological conditions, an enhanced expression of CB1R is observed in the hepatic cells, which contributes to the hepatic insulin resistance, fibrosis, lipogenesis, and steatosis." (PMID 31035653, 2019). "Upon administration of the extracellular CTSD inhibitor, we observed that HFD-fed rats showed a significant reduction in plasma insulin levels and improvement of steatosis, two important characteristics of diet-induced NAFLD." (PMID 31060228, 2019). "We confirmed that ER stress-mediated hepatic steatosis is modulated by FoxO1 through insulin signaling in aged db/db mice." (PMID 31246177, 2019). "Muscle weight is also lower in PpargΔ/Δ mice than in control littermates, most likely because of impaired metabolic homeostasis and steatosis in these mice, as these conditions have been shown to alter insulin and anabolic signaling in other settings." (PMID 30011852, 2018). "Glucose-6-phosphatase mRNA, encoding an important enzyme for glycogenolysis and glucose production, was increased (>7-fold, p < 0.001) already after 7 days after steatosis induction with a combination of free fatty acids, glucose and insulin." (PMID 30250238, 2018). "The KKAy mice are tipical T2DM animal model with obese, hyperglycemic, hyperinsulinemic, insulin resistant, and obvious hepatic steatosis." (PMID 29593573, 2018). "For this purpose, the monosaccharide fructose was used together with supraphysiological concentrations of insulin to induce steatosis." (PMID 30250238, 2018). "In summary, we found that miR-122 inhibition in liver organoids leads to liver inflammation, necrosis, fibrosis, steatosis as well as dysregulation in lipid metabolism as well as insulin signaling." (PMID 30024933, 2018). "The effect of insulin concentration on lipid accumulation was found to be of minor importance for steatosis induction in the presence of FFA." (PMID 30250238, 2018). "Impaired insulin signaling further increased the hepatic TG accumulation and steatosis in dairy cows." (PMID 29882814, 2018). "USS steatosis and elevated ALT were positively associated with insulin, and elevated ALT and AST positively associated with CRP, although these were imprecisely estimated with wide CIs." (PMID 30687796, 2018). "Exposure of cells to fatty acids has been employed to model NAFLD in cell culture systems with various reports of effects on steatosis, insulin signalling and activation of apoptosis pathways." (PMID 29786565, 2018).
steatosis (continued). "Increasing fatty acid oxidation by PPARα activation can lower circulating triglyceride levels, decrease liver and muscle steatosis, and reduce adiposity, which improves insulin sensitivity." (PMID 30021644, 2018). "GLP-1 analogues stimulate insulin secretion by pancreatic beta cell and inhibit glucagon release; Liraglutide is the most used drug in this class and significantly improves steatosis, hepatocyte ballooning and transaminase levels." (PMID 30413050, 2018). "A series of studies have shown that increased ceramide level in both liver and plasma coincide with the development of liver dysfunction, hepatic insulin resistance, and steatosis in rodents." (PMID 28827783, 2017). "Dose response data shows that maximal effects of glucagon and TNF alpha for reduction or reversal of insulin-induced steatosis are active at >1 μg/ml glucagon and 100 nM TNF alpha, respectively." (PMID 29430572, 2017). "Aliskiren normalized plasma glucose and insulin levels, reduced cholesterol, triglycerides and total fat accumulation in liver and diminished hepatic injury, steatosis and fibrosis." (PMID 29046730, 2017). "Pancreatic islets delivered to the hepatic sinusoids engraft and produce insulin, and focal steatosis is observed in 20% to 60% of islet recipients." (PMID 28742102, 2017). "Gender differences in WD-induced steatosis, insulin sensitivity, and predicted microbiota functions were all FXR-dependent." (PMID 28496104, 2017). "Increased urinary excretion of microbial metabolites from co-metabolic processing of choline has also been related to steatosis, fatty liver, and insulin resistance in animals fed high-fat diets." (PMID 28403191, 2017). "(ii) We compared the percentage reversal of 6 d insulin-induced steatosis at 9 day exposure to vehicle." (PMID 29430572, 2017). "Aliskiren normalized plasma glucose and insulin levels, reduced hepatic total fat, cholesterol and triglycerides accumulation, thus diminishing steatosis, oxidative stress and fibrosis in liver." (PMID 29046730, 2017). "Meanwhile, lipid accumulation, insulin resistant, oxidative stress and inflammation response have been widely suggested to play a pivotal role in the transition from steatosis to NASH." (PMID 28820447, 2017). "In adipocytes and hepatocytes insulin and nutrient excess drive lipid droplet accumulation and steatosis." (PMID 29430572, 2017). "Our data revealed that male WD-fed FXR KO mice had the most severe steatosis and highest hepatic and serum lipids as well as insulin resistance among the eight studied groups." (PMID 28496104, 2017). "From a clinical point of view, our study suggests that PCOS patients should be assessed for presence of steatosis, especially those with reduced insulin sensitivity and/or hyperandrogenism." (PMID 29161258, 2017). "Taken together, hepatic Fas overexpression was sufficient to induce steatosis and impaired insulin sensitivity, suggesting that Fas is a potent regulator of both hepatic lipid metabolism and insulin sensitivity." (PMID 28883393, 2017). "There were significant improvements in steatosis, serum transaminases and insulin sensitivity in both groups over the study period." (PMID 28419124, 2017). "Treatment with BAR502 caused a ≈10% reduction of b.w., increased insulin sensitivity and circulating levels of HDL, while reduced steatosis, inflammatory and fibrosis scores and liver expression of SREPB1c, FAS, PPARγ, CD36 and CYP7A1 mRNA." (PMID 28202906, 2017). "Rosiglitazone was shown to improve steatosis, transaminase levels, adiponectin and insulin sensitivity, despite evidence of significant weight gain compared to placebo." (PMID 27006654, 2016). "There was a significant negative correlation between adherence to Mediterranean diet and ALT, insulin levels, stage of fibrosis, severity of steatosis, and the likelihood of having NASH." (PMID 27006654, 2016).